ZCCHC4 (zinc finger CCHC-type containing 4)
Description:
rRNA N6-methyltransferase that specifically methylates the adenine in position 4220 of 28S rRNA. N6-methylation of adenine(4220) in 28S rRNA is required for translation.
Synonyms: HSPC052; FLJ23024; ZGRF4
Tractability: Small molecule: a structure with a bound ligand is known. PROTAC: ubiquitination databases record sites on it.
Gene: Protein-coding gene on chromosome 4 (25,312,774 to 25,372,306, forward strand). Ensembl gene ENSG00000168228.
Subcellular location: Nucleus, nucleolus; Cytoplasm
Subcellular location (Human Protein Atlas): Golgi apparatus; Nuclear speckles
Gene Ontology:
Molecular function: rRNA (adenine-N6-)-methyltransferase activity; S-adenosyl-L-methionine binding; zinc ion binding; methyltransferase activity; nucleic acid binding; S-adenosylmethionine-dependent methyltransferase activity
Biological process: positive regulation of translation; rRNA methylation
Cellular component: cytoplasm; nucleolus
Genetic constraint (gnomAD): Loss-of-function variants: 34 observed, 45.46 expected, observed/expected ratio (o/e) 0.75, 90% interval 0.57 to 1. The upper end of that interval is the gene's LOEUF score, 1, which puts it in group 4 of 6, group 1 being the genes least tolerant of losing a copy. Missense variants: 462 observed, 476.01 expected, observed/expected ratio (o/e) 0.97, 90% interval 0.9 to 1.05. Synonymous variants: 158 observed, 170.33 expected, observed/expected ratio (o/e) 0.93, 90% interval 0.81 to 1.06.
Homologues: Orthologues: chimpanzee ZCCHC4 (99% identical), rabbit ZCCHC4 (88% identical), pig ZCCHC4 (87% identical), dog ZCCHC4 (84% identical), guinea pig ZCCHC4 (81% identical), mouse Zcchc4 (76% identical), rat Zcchc4 (75% identical), tropical clawed frog zcchc4 (61% identical), zebrafish zcchc4 (53% identical), Drosophila melanogaster CG12863 (29% identical), Caenorhabditis elegans F33A8.4 (25% identical).